ENTR1 (endosome associated trafficking regulator 1)
Description:
Endosome-associated protein that plays a role in membrane receptor sorting, cytokinesis and ciliogenesis. Involved in the endosome-to-plasma membrane trafficking and recycling of SNX27-retromer-dependent cargo proteins, such as GLUT1. Involved in the regulation of cytokinesis; the function may involve PTPN13 and GIT1. Plays a role in the formation of cilia. Involved in cargo protein localization, such as PKD2, at primary cilia. Involved in the presentation of the tumor necrosis factor (TNF) receptor TNFRSF1A on the cell surface, and hence in the modulation of the TNF-induced apoptosis (By similarity).
Synonyms: SDCCAG3; NY-CO-3; SDDAG3
Tractability: PROTAC: ubiquitination databases record sites on it.
Gene: Protein-coding gene on chromosome 9 (136,401,922 to 136,410,614, reverse strand). Ensembl gene ENSG00000165689.
Subcellular location: Cytoplasm; Early endosome; Endosome; Recycling endosome; Midbody; Cytoplasm, cytoskeleton, microtubule organizing center, centrosome; Cytoplasm, cytoskeleton, cilium basal body
Gene Ontology:
Molecular function: protein binding
Biological process: endocytic recycling; positive regulation of cilium assembly; positive regulation of protein localization to cilium; regulation of cytokinesis
Cellular component: centrosome; ciliary basal body; early endosome; endosome; midbody; recycling endosome; retromer complex; cytoplasm
Genetic constraint (gnomAD): Loss-of-function variants: 40 observed, 38.92 expected, observed/expected ratio (o/e) 1.03, 90% interval 0.8 to 1.34. The upper end of that interval is the gene's LOEUF score, 1.34, which puts it in group 5 of 6, group 1 being the genes least tolerant of losing a copy. Missense variants: 614 observed, 530.18 expected, observed/expected ratio (o/e) 1.16, 90% interval 1.08 to 1.24. Synonymous variants: 273 observed, 234.8 expected, observed/expected ratio (o/e) 1.16, 90% interval 1.05 to 1.28.
Homologues: Orthologues: chimpanzee ENTR1 (99% identical), macaque ENTR1 (97% identical), dog ENTR1 (84% identical), guinea pig ENTR1 (81% identical), pig ENTR1 (80% identical), rat Entr1l3 (79% identical), mouse Entr1 (67% identical), tropical clawed frog entr1 (34% identical), zebrafish entr1 (26% identical).
Diseases named in the same sentence as ENTR1 in open-access papers:
ENTR1 is named in the same sentence as 14 diseases in open-access papers, as found by Europe PMC text mining. Sharing a sentence is not in itself a finding about the gene and the disease. The quoted sentences say what the papers report.
colon cancer (6 papers, 2013 to 2023). "Moreover, the FERM domain allows the interaction of PTPN13 with other proteins, such as serologically defined colon cancer antigen 3/endosome-associated trafficking regulator 1 (SDCCAG3/ENTR1) that is overexpressed in colon cancer and is involved in cytokinesis regulation." (PMID 33322542, 2020). "ENTR1, located on chromosome 9, q34.3, was originally identified as an antigen in serum derived from colon cancer patients and was called serologically defined colon cancer antigen 3 (SDCCAG3) with two major splicing variants." (PMID 37182178, 2023). "78% of the colon cancer samples with elevated ENTR1 and 73% of the colon cancer samples with elevated PTPN13 showed downregulation of Fas expression." (PMID 31308371, 2019). "Interestingly, when comparing the expression of ENTR1/PTPN13 with Fas a significant proportion of colon cancer samples exhibit upregulated ENTR1 or PTPN13 and concomitantly downregulation of Fas expression levels." (PMID 31308371, 2019). "ENTR1 was originally identified as an antigen in serum derived from colon cancer patients." (PMID 31308371, 2019). "We confirmed our previous finding that ENTR1 is upregulated in colon cancer tumours compared to non-tumorous tissue, similarly we also observed elevated PTPN13 expression in colon cancer tissue samples, whereas Fas expression was downregulated." (PMID 31308371, 2019). "This prompted us to investigate expression levels of ENTR1, PTPN13 and Fas in colon cancer samples." (PMID 31308371, 2019).
Hyperinsulinemia (1 paper, 2019). An increased concentration of insulin in the blood. "The control of SLC2A1 by ENTR1 in the context of the equine athlete is intriguing to speculate since SLC2A1 is expressed within equine lamellar tissue, and its expression is increased in hyperinsulinemia, therefore may play a role in the pathophysiology of equine laminitis." (PMID 31850069, 2019).
tumor (4 papers, 2013 to 2023). "The association of ENTR1 with tumor-infiltrating immune cells in the high- and low-expression groups was analyzed using the CIBERSORT algorithm." (PMID 37182178, 2023). "Consistent with the differential mRNA expression analysis result, the corresponding protein expression levels of ENTR1 were found to be higher in tumor samples." (PMID 37740762, 2023). "The AAGAB and the ENTR1 expressions showed significant differences in the different T stages and different tumor stages." (PMID 37740762, 2023).
cancer (2 papers, 2013 to 2023). A tumor composed of atypical neoplastic, often pleomorphic cells that invade other tissues. "The TMEM251, AAGAB, ENTR1, SCYL2, and WDR72 were all found to be expressed mainly in cancer cells." (PMID 37740762, 2023).
ENTR1 also shares sentences with these, for which no sentence is quoted: airway hyperresponsiveness (1 paper); bronchial hyperreactivity (1); colorectal mucinous adenocarcinoma (1); Impaired glucose tolerance (1); Insulin resistance (1); lipid metabolism disorders (1); metabolic disorders (1); Obesity (1); polycystic kidney disease (1); prostate carcinoma (1).